HMGA1 (high mobility group AT-hook 1)
Diseases named in the same sentence as HMGA1 in open-access papers (continued):
Sharing a sentence is not in itself a finding about the gene and the disease.
tumor (continued). "Enrichment analysis further indicated that HMGA1 regulates pathways central to tumor cell proliferation and survival, including cell cycle progression, DNA replication, proteasome activity, and pyrimidine metabolism." (PMID 41463532, 2025). "The results demonstrated that knockdown of LUCAT1 led to the downregulation of multiple key tumor regulatory genes, including HMGA1." (PMID 40025525, 2025). "First, immunohistochemistry images from the HPA database demonstrated that HMGA1 is highly expressed in tumour tissues compared to normal tissues." (PMID 40988131, 2025). "We conducted pertinent in vitro research centered on the HMGA1 gene to investigate its function as a principal transcription factor in C2 MKI67+ tumor cells." (PMID 40842994, 2025). "Previous studies have shown that HMGA1 performs oncogenic functions and promotes tumor progression by regulating autophagy, angiogenesis, epithelial-mesenchymal transition, cell cycle, and chemotherapy resistance." (PMID 40288645, 2025). "To further investigate the role of extracellular HMGA1 in tumor proliferation, we aimed to quantify HMGA1 in the CM." (PMID 41145488, 2025). "Collectively, these data suggest that NUDT16 enhances the ability of tumor cells to cope with replication stress by reversing the PARylation and positively regulating the protein expression of HMGA1." (PMID 40288645, 2025). "HMGA1 has been reported to act as a structural transcription factor to promote the transcription of oncogenes and tumor progression by regulating autophagy, angiogenesis, and epithelial-mesenchymal transition." (PMID 40288645, 2025). "Given the fundamental role for Wnt signaling in colon tumorigenesis and HMGA1-dependent upregulation of Wnt genes and β-catenin levels in our tumor models, we further examined the relationship between HMGA1 and Wnt genes." (PMID 39895630, 2025). "High mobility group A1 (HMGA1) promotes tumor progression by regulating autophagy, angiogenesis, and chemoresistance; however, its role in coordinating replication stress and cell cycle progression remains elusive." (PMID 40288645, 2025). "Chromatin accessibility associated with high HMGA1 in JAK2V617F AML cell lines includes gene loci involved in proliferation and signal transduction, pathways that are regulated by HMGA1 in diverse tumor settings." (PMID 40076747, 2025). "In contrast, HMGA1 was significantly more expressed in tumor-derived epithelial cells compared to their healthy counterparts." (PMID 41145488, 2025). "Intriguingly, HMGA1 fosters both tumor progression and fibrosis in models of pancreatic carcinogenesis, much like its activity in MPN progression." (PMID 40076747, 2025). "We demonstrate that HMGA1 is not only a ubiquitous marker of aggressive disease but also a key driver of a stem-like, immunosuppressive tumor microenvironment and a novel determinant of resistance to AKT inhibition." (PMID 41463532, 2025). "This high-resolution approach revealed that HMGA1 exhibits conserved expression patterns within tumor immune microenvironments, with particularly strong expression in immunosuppressive cell populations." (PMID 41463532, 2025). "Colony formation assays showed that HMGA1 knockdown significantly reduced the proliferative capacity of tumour cells." (PMID 40988131, 2025). "These assays revealed a positive correlation between LUCAT1 and HMGA1 in BC, and this correlation was verified in clinical BC tumour samples." (PMID 40025525, 2025). "The level of high mobility group A1 (HMGA1) increases especially in highly proliferative cells, possibly related to its regulatory role in tumor migration, invasion and stemness." (PMID 40660393, 2025). "To evaluate how HMGA1 relates to the tumor microenvironment (TME), we examined ESTIMATE stromal and immune scores." (PMID 41463532, 2025).
tumor (continued). "The small intestinal tumor burden is also greater in ApcMin/+ mice with intact HMGA1, indicating that HMGA1 contributes to tumorigenesis in both the colon and small intestine of Min mice." (PMID 39895630, 2025). "First, using the CDX2P-CreERT2Apcfl/fl mouse model, the authors showed that knockout of Hmga1 in the mice reduced tumor burden and extended their survival." (PMID 39895631, 2025). "In this study, we found that the expression of HMGA1 was higher during the S phase, while inhibition of HMGA1 reduced the stability of replication forks and proliferation of tumor cells." (PMID 40288645, 2025). "We identified 90 significantly upregulated and 11 downregulated phosphoproteins, shedding light on the specific phosphorylation changes driven by extracellular HMGA1 and their possible contribution to tumor aggressiveness." (PMID 41145488, 2025). "In our experiments, subcutaneous tumour grafting and orthotopic EC models demonstrated that HMGA1 interference or gene knockout significantly inhibited EC tumorigenesis, an effect that was further enhanced by olaparib treatment." (PMID 39690136, 2024). "Compared with other genes in the model, tumor cells had obviously transcriptional levels and the highest expressed fraction of HMGA1." (PMID 38329444, 2024). "Given that FKBP12 facilitates the intracellular accumulation of rapamycin, elevated expression of FKBP12 induced by HMGA1 in tumor cells offers the possibility of enhancing drug accumulation within the tumor." (PMID 38725843, 2024). "Immunohistochemical staining of tumor sections revealed knockdown of HMGA1 resulted in the decrease of HMGA1 and FKBP12 in murine tumors." (PMID 38725843, 2024). "Patients and Methods: In this research, we compared HMGA1 mRNA expression between tumor tissues and normal samples and evaluated the correlations with clinical characteristics in LUAD patients based on the data of TCGA database." (PMID 38706894, 2024). "Tumours from WT‐AKR cells were not significantly inhibited by olaparib, whereas tumours with HMGA1 depletion showed marked inhibition with olaparib treatment." (PMID 39690136, 2024). "It was found that the expression of Ki‐67 proliferation antigen and HMGA1 was significantly weaker in the NAT10 knockdown tumor tissues compared with the control group." (PMID 38922788, 2024). "We provided several lines of evidence demonstrating that HMGA1 plays a critical role in maintaining intracellular redox balance and promoting tumor proliferation by cooperating with ATF4 to activate the transcription of SLC7A11." (PMID 38383528, 2024). "Tissue immunofluorescence confirmed that olaparib enhanced DNA damage in tumours with HMGA1 knockdown." (PMID 39690136, 2024). "In order to study the effect of TKT inhibition on HMGA1-induced tumor progression, we applied TKT inhibitor OT or PBS into mice by gavage every day." (PMID 39080260, 2024). "Immunohistochemistry revealed only weak upregulation of DNA damage markers (γ‐H2AX) due to HMGA1 interference alone, but olaparib treatment led to significant DNA damage in tumours with HMGA1 knockdown." (PMID 39690136, 2024). "Upregulation of HMGA1, while enhancing the self-renewal and invasive capabilities of the tumor, also sensitizes the tumor to specific drugs such as rapamycin." (PMID 38725843, 2024). "NHEJ repair proteins, Ku70 and p‐DNA‐PKcs, were also significantly decreased in tumours treated with both HMGA1 knockdown and olaparib." (PMID 39690136, 2024). "Together, our data indicate that elevated HMGA1 promotes cell proliferation and tumor growth in ESCC." (PMID 39080260, 2024). "Relevant animal experiments were also synchronously validated and si-HMGA1 groups down-regulated xenograft growth including the weights and size in tumor xenografts." (PMID 38706894, 2024).
tumor (continued). "In the term of molecular mechanisms, HMGA1 acted as a crucial regulator of tumor-promoting macrophage recruitment by activating NF-κB-CCL2 signaling and also regulated PD-L1 expression to promote immunosuppression." (PMID 38329444, 2024). "Last, HMGA1 was chosen as the representative biomarker, and analysis of the in-house cohort showed that HMGA1 was highly expressed in tumor tissues and correlated with decreased T cell infiltration." (PMID 38329444, 2024). "A Additionally, HMGA1 expressed was negatively correlated with ImmuneScore, but positively with tumor purity in multiple independent cohorts, suggesting the guidance of HMGA1 in distinguishing the hot and cold NSCLC tumors." (PMID 38329444, 2024). "In this study, we further explored the relationship among STMN1, HMGA1, microtubule stability and tumor metastasis." (PMID 38385074, 2024). "Silencing HMGA1 obviously decreased the proliferation of the syngeneic tumor, resulting in smaller tumor size and mass compared to the control group." (PMID 38725843, 2024). "For example, we found that certain genes, such as HMGA1 or TEAD1, are recurrently associated with GPCRs' expression across multiple tumor subtypes." (PMID 38723607, 2024). "The growth curves of tumor xenograft volumes were significantly reduced in the si-HMGA1 group (p<0.05)." (PMID 38706894, 2024). "We found that HMGA1 expression was significantly higher in tumor tissues than in para-tumor tissues, and HMGA1 was specifically expressed in NSCLC." (PMID 38329444, 2024). "In this research, we compared HMGA1 mRNA expression between tumor tissues and normal samples and evaluated the correlations with clinical characteristics in LUAD patients based on the data of TCGA database." (PMID 38706894, 2024). "The LC‒MS/MS results illustrated that HMGA1 is a potential protein that interacts with STMN1 and is significantly associated with tumor metastasis." (PMID 38385074, 2024). "The results proved that si-HMGA1 group inhibited xenograft growth including the weights and size in tumor xenografts." (PMID 38706894, 2024). "Univariate and multivariate analyses indicated that both HMGA1 expression and tumor T stage were independent predictive factors, and the low expression of HMGA1 and early T stage implied a better prognosis." (PMID 36705364, 2023). "We found that the risk features of HMGA1 and FOXM1 in LUAD were closely related to patients’ gender, tumor stage and T classification, while HMGA1 was also correlated with N classification (p < 0.05)." (PMID 37240870, 2023). "Intriguingly, tumors that formed from the pool of cells with HMGA1 silencing (E3LZ10.7 and AsPC-1 cells) express higher HMGA1 than the injected cells, suggesting that escape from gene silencing and a specific level of HMGA1 is required for tumor formation." (PMID 36919699, 2023). "This sample harbored also an HMGA1 rearrangement and the tumor displayed an HMGA‐type expression profile, suggesting that the COL4A5–COL4A6 deletion is a secondary event." (PMID 35822448, 2023). "HMGA1, which is overexpressed in ESCs and downregulated in differentiated tissues, accumulates in virtually all tumor types." (PMID 37176013, 2023). "METTL3 promoted HMGA1 expression in an m6A-dependent manner, which induced tumor cell proliferation and tumor growth in CRC." (PMID 37152066, 2023). "Taken together, these results indicate that HMGA1 drives PDAC tumor initiation, progression, and stroma formation, at least in part, by inducing FGF19 expression and secretion." (PMID 36919699, 2023). "Seminal work, based on AP-1 inhibition by a c-JUN dominant-negative derivative, showed that HMGA1 was an essential AP-1 target gene in the tumor-promoter-induced transformation." (PMID 37176013, 2023). "In conclusion, the existence of the HMGA1 high-tumor stem cell subgroup is closely related to tumor metastasis and drug resistance." (PMID 37858183, 2023).
tumor (continued). "Together, our findings reveal a unique role for HMGA1 in tumor progression and “building” a stromal wall through FGF19 and highlight a new therapeutic target for a subset of highly recalcitrant tumors." (PMID 36919699, 2023). "The overexpression of HMGA1 is related to the malignant degree of the tumor, and knockdown of HMGA1 can reduce the proliferation and invasion ability of OC cells in vitro." (PMID 36776216, 2023). "RNA sequencing revealed HMGA1 transcriptional networks governing proliferation and tumor-stroma interactions, including the FGF19 gene." (PMID 36919699, 2023). "In mice with human PDAC xenografts, silencing HMGA1 or FGF19 depletes tumor-initiating cells while disrupting tumor growth and stroma formation." (PMID 36919699, 2023). "Here, we uncover an epigenetic program whereby HMGA1 upregulates FGF19 during tumor progression and stroma formation." (PMID 36919699, 2023). "Hmga1 haploinsufficiency within pancreatic ductal epithelium is sufficient to mitigate tumor and stroma formation in KPC mice." (PMID 36919699, 2023). "As a non-histone chromatin protein, the high-mobility group AT-Hook 1 (HMGA1), which is highly expressed in embryos and barely detectable in adult tissues, is repopulated in tumor cells." (PMID 37240870, 2023). "As a characteristic molecule of the HMGA1 high-tumor stem cell subgroup—"HMGA1", a transcription factor, it regulates the transcription of target genes by altering chromatin structure and interacting with other transcription factors." (PMID 37858183, 2023). "HMGA1 deficiency also depletes tumor-initiating cells in both cell lines (E3LZ10.7 and AsPC-1), demonstrating that HMGA1 is required for tumor initiation and growth in xenograft models." (PMID 36919699, 2023). "Comparatively, the risk characteristics of HMGA1 and FOXM1 in LIHC were correlated with patients’ grade, tumor stage and T classification (p < 0.05)." (PMID 37240870, 2023). "The xenografts with HMGA1-silencing HUCCT1 cells exhibited decreased tumor volumes, weights and metastatic lesions compared with shRNA, substantiating the procarcinogenic role of HMGA1 in iCCA." (PMID 36978140, 2023). "We further detected the expression of HMGA1 in iCCAs and paired tumor-adjacent tissues with qPCR and western blot (WB) which demonstrated that HMGA1 was significantly upregulated in iCCAs." (PMID 36978140, 2023). "Deletion of macrophages with clodronate liposomes significantly abrogated the tumor-promoting effects of HMGA1 on HCC growth." (PMID 35785026, 2022). "What's more, the expression of HMGA1 pseudogenes increases with tumor stage progression, which is consistent with the expression pattern of HMGA1." (PMID 35864955, 2022). "Reassuringly, we found a decrease in AFP and OPN and an increase in HMGA1 and Hep-Par1 staining in Myc-R26Met versus Alb-R26Met tumours." (PMID 36433941, 2022). "As neo-adjuvant chemotherapy, trabectedin reduces HMGA1 expression in the treatment of myxoid LPS to play a potent anti-tumor activity." (PMID 35864955, 2022). "In HCC, HMGA1 has been reported to promote tumor growth and metastasis and is a potential prognostic factor." (PMID 35785026, 2022). "This also suggests that the modified HMGA1 protein is involved in the regulation of tumour progression." (PMID 35864955, 2022). "In endometrial cancer, LINC00665 can directly bind to the HMGA1 protein to promote tumor metastasis and invasion." (PMID 35563845, 2022). "A posterior work demonstrated that HMGA1 interacts with the TF FOXM1 to promote tumour angiogenesis in TNBC through the transcriptional activation of vascular endothelial growth factor A (VEGFA)." (PMID 35267409, 2022). "HMGA1 is a potent oncogene that triggers tumour progression and is related to undifferentiated stem-like phenotypes and aggressiveness." (PMID 36433941, 2022).
tumor (continued). "To assess the efficacy of the combination of paclitaxel treatment with HMGA1 depletion on mouse tumour burden, we measured the volume of the tumour at the endpoint of the treatment when mice were sacrificed." (PMID 35504904, 2022). "Deletion of macrophage in HCC tissues largely blocked the tumor-promoting effects of HMGA1 on HCC tumor growth." (PMID 35785026, 2022). "With abnormally expression in most aggressive tumors, high expression of HMGA1 portends poor differentiation of tumor cells and adverse clinical outcomes of patients." (PMID 36479041, 2022). "Recent studies on mouse intestinal stem cells (ISC) have shown that HMGA1 is capable of maintaining Wnt and other pathways and that HMGA1 overexpression promotes tumor development." (PMID 36536279, 2022). "Collectively, these studies reveal that HMGA1 has an essential role in tumorigenesis and tumor progression." (PMID 36251702, 2022). "Conversely, some well-known factors related to tumor growth promotion, such as HMGA1, GTF3A, PHF19, CENPX, and MBD2, were upregulated." (PMID 35935940, 2022). "The restoration of miR-214-3p limits EWS cell growth and migration and represses the expression of its target HMGA1, supporting the potential role of this miRNA as a marker of tumor aggressiveness." (PMID 35406534, 2022). "More recently, it has been found that HMGA1 can promote a variety of malignant phenotypes of cancer cells, and it has a high expression level in tumor tissues." (PMID 36304135, 2022). "We screened the changes of HMGA1 expression levels in the blood and noted the expression tends to decrease after surgical removal of the tumor over time." (PMID 35948739, 2022). "In TNBC, HMGA1 is overexpressed and coordinates a gene network that controls cellular processes involved in tumour development, progression, and metastasis formation." (PMID 35504904, 2022). "As displayed by in vivo imaging analysis, HMGA1 overexpression remarkably increased tumor burden in immune-competent mice." (PMID 35785026, 2022). "Contrary to normal somatic cells, the levels of HMGA1 products are often increased in tumor-transformed cells and correlate with the advancement of the disease or the ability to metastasize." (PMID 35948739, 2022). "Numb has an asymmetric division of stem cells, and HMGA1 can negatively regulate the expression of Numb and promote the development of tumours by binding to the promoter of Numb or affecting miR-146a at the posttranscriptional level." (PMID 35864955, 2022). "The existing findings indicate a key role of HMGA1 in regulating tumor metastasis and predicting prognosis." (PMID 36479041, 2022). "A large number of studies have confirmed that HMGA1 regulates genes related to tumours in the reproductive system, digestive system, urinary system and haematopoietic system." (PMID 35864955, 2022). "When macrophages were depleted, however, the tumor-promoting roles of HMGA1 were significantly blocked." (PMID 35785026, 2022). "Taken together, these data indicate that HMGA1 promotes tumor growth of HCC, at least, in part, dependent on macrophage infiltration." (PMID 35785026, 2022). "HMGA1 is also a central factor in tumor progression in patients with triple-negative breast cancer and pancreatic cancer." (PMID 34072941, 2021). "As a result, the expression of HMGA1 was correlated with the degree of tumor differentiation, and CCAs with poor differentiation exhibited higher expression of HMGA1." (PMID 34716319, 2021). "Our findings indicated that HMGA1 promoted tumor progression via elevating TRIP13 transcription and expression." (PMID 33648560, 2021). "We next assessed the potential role of HMGA1 in tumor growth by establishing a subcutaneous xenograft model using HUCCT1 (n = 5) and QBC939 cells (n = 6) with HMGA1 knockdown or overexpression." (PMID 34716319, 2021).